EGFR (epidermal growth factor receptor)
Diseases named in the same sentence as EGFR in open-access papers (continued):
Sharing a sentence is not in itself a finding about the gene and the disease.
tumor (continued). "The detection of circulating tumor DNA (ctDNA) in plasma has become an important biomarker in recent years for the diagnosis of theragnostic mutations (e.g., EGFR and lung cancer)." (PMID 34359795, 2021). "Neratinib is also under evaluation in tumours with either EGFR mutation or amplification in phase II study." (PMID 33680090, 2021). "AKAP12, another ERK1/2 inhibitor, was found preferentially upregulated in FGFR tumors, whereas RALT/ERRFI1, an EGFR inhibitor and degradation promoter, was strongly overexpressed only in the F2T2↑ tumor, explaining its paradoxical EGFR expression loss." (PMID 33853673, 2021). "We sought to determine the cell death pattern in the patient-derived tumor cells with the sensitive-mutation EGFR." (PMID 34367939, 2021). "NGS identified a long list of non-EGFR mutations related to tumor initiation and progression, adding additional therapeutic opportunities and/or assessing the prognostic outcomes for NSCLC patients." (PMID 34257561, 2021). "This study investigated the anti-tumour activity and safety profile of first-line afatinib in previously-untreated elderly Japanese patients with EGFR mutation-positive non-small cell lung cancer (NSCLC)." (PMID 33648453, 2021). "These methylation statuses of c-MET and EGFR in CRC were also consistently associated with the tumor stage, dysfunctional T cell phenotypes, and shorter OS of CRC patients." (PMID 34512327, 2021). "During the last decade, liquid biopsies to detect EGFR mutations in circulating tumor DNA (ctDNA) have been developed and demonstrate good sensitivity (between 62 and 75%) and specificity (between 79 and 96%)." (PMID 33652831, 2021). "Among them, EGFR mutation represents an important tumor cell biomarker linked with HPD after immunotherapy." (PMID 34113560, 2021). "The efficiency of anti-EGFR depends on the KRAS/BRAF mutation status, as it was demonstrated that BRAF-mutated tumours had reduced response rates to anti-EGFR, even though they were KRAS wild-type." (PMID 34945008, 2021). "Loss of EphA2 reduced the proliferation of erlotinib-resistant tumor cells with the EGFR (T790M) mutation in vitro and in vivo, in TKI-resistant EGFR L858R+790M transgenic mice." (PMID 33572284, 2021). "Radiomic features and conventional parameters (metabolic tumor volume and SUVmax) were proved to predictive of EGFR mutation in NSCLC." (PMID 33995277, 2021). "Tumor genomic testing revealed that 28 patients (37%) carried an EGFR mutation, and three (4%) had an ALK/ROS1 rearrangement." (PMID 33794813, 2021). "A systematic review and meta-analysis involving 4527 advanced NSCLC patients indicated that compared to tumor tissue, the combined sensitivity and specificity of ctDNA EGFR mutation in plasma samples was 0.70 and 0.98, respectively." (PMID 35049681, 2021). "Both of these drugs have been highly effective in other tumor types, particularly lung cancer harboring mutations of the EGFR gene." (PMID 33827580, 2021). "Accordingly, the use of primary tumor gene expression profiles as a basis for CMS classification in the clinical trial cohorts likely impacted the analyses of associations to anti-EGFR versus anti-VEGF therapy response." (PMID 34262039, 2021). "In the WT EGFR subgroup analysis, IL-17A rs8193036 T-allele carriers had higher risks of developing an advanced tumor stage (p = 0.016) and lymphatic invasion (p = 0.049)." (PMID 33802737, 2021).
tumor (continued). "Novel strategies targeting EREG/EGFR, tumor-associated macrophages, and alternative activation oncoproteins are under development or undergoing clinical trials." (PMID 34884633, 2021). "The full potential of DR can be seen when DR is used in combination with therapeutic strategies, such as EGFR inhibitors, where all relevant tumor-associated phenotypes are rescued." (PMID 34766923, 2021). "In the present investigation, we found that CALM1 and EGFR were remarkably up-regulated in ESCC, compared with paired NAT and that over-expression of CALM1 and EGFR in ESCC was significantly associated with tumor progression and poor overall prognosis." (PMID 33602237, 2021). "Epidermal growth factor receptor tyrosine kinase inhibitors (EGFR-TKIs) are effective in advanced EGFR-mutation non-small cell lung cancer (NSCLC) but the magnitude of tumor regression varies, and drug resistance is unavoidable." (PMID 34168988, 2021). "All the genes within the detection range are included in the TMB (tumor mutation burden) calculation, excluding the kinase region mutations of EGFR and ALK, and the total number of CNV and fusion." (PMID 34168983, 2021). "In conclusion, this study offers novel evidence that TCR repertoires are related to tumor status and gene mutation and that different EGFR mutation subtypes are correlated with TCR clonality and the Shannon index." (PMID 33777727, 2021). "In conclusion, this study indicated that vesicular RNA contributes a consistent picture of tumor heterogeneity and the relative abundance of EGFR mutations in NSCLC patients receiving TKIs." (PMID 33942501, 2021). "Overexpression or activating mutation of the EGFR promotes tumor proliferation, angiogenesis, and metastasis and so on." (PMID 33414368, 2021). "In a multivariate analyses of tumor location, resection status, and EGFR mutational status were associated with improved OS." (PMID 34513663, 2021). "It has been reported that the number and proportion of tumor cells in samples will affect the detection rate of EGFR gene mutation." (PMID 34034456, 2021). "In this study, we isolated tumor‐derived exosomes from the plasma of EGFR mutation and wild‐type NSCLC patients." (PMID 33682961, 2021). "EGFRvIII is a variant of EGFR present in 31–64% of patients with GB that promote tumor cell proliferation, invasion, and angiogenesis in the tumor environment." (PMID 35011678, 2021). "Herein, our report represents a remarkably interesting case of the complexity and heterogeneity of EGFR mutations along the treatment course of different TKIs via NGS-based tumor tissue and liquid biopsy." (PMID 34397683, 2021). "ctDNA, as a specific tumour marker, has a high specificity of 80-95% for the detection of EGFR mutations, which can inform on the use of tyrosine kinase targeted therapies." (PMID 35127511, 2021). "EGFR signaling, one of the most dysregulated pathways in various cancers, is highly associated with tumor progression, chemoresistance, and metastasis through its downstream signaling pathway, such as PI3K/AKT signaling." (PMID 34445562, 2021). "EGFR expression is associated with tumor cell proliferation, angiogenesis, tumor invasion, metastasis, and inhibition of apoptosis." (PMID 34484402, 2021). "Further investigation identified a threonine to methionine mutation at codon 790 (T790M) within exon 20 in tumours of patients who relapse following treatment with first-generation EGFR TKIs." (PMID 34572879, 2021). "About the characteristics of LADC, the tumor cells in EGFR mutation group revealed a higher rate of well differentiation (p < 0.001)." (PMID 33799753, 2021).
tumor (continued). "At the single‐patient level, we detected a complex picture of tumor heterogeneity supported by combinations of driver EGFR mutations, sporadically seen also at ctDNA level, at the baseline, and two consecutive liquid biopsies." (PMID 33942501, 2021). "Epidermal growth factor (EGF)/EGFR signaling has been implicated in many steps in the processes of tumor invasion and metastasis." (PMID 34163029, 2021). "In NSCLC, over 60% of EGFR mutations are associated with tumor proliferation, neovascularization, and metastasis." (PMID 33025047, 2021). "Combining a molecular marker (RAS mutational analysis) with a clinical characteristic (tumour sidedness), the patient population most likely to benefit from anti-EGFR strategy can be defined." (PMID 33154570, 2021). "While many tumours harbour mutations in key IFN genes or epigenetically silence them, the activation of oncogenic pathways or loss of tumour suppressors such as EGFR, Wnt B catenin, or Pten, all have links to IFN production or responsiveness." (PMID 33807553, 2021). "When considering the use of TAGRISSO, EGFR mutation status in tumour or plasma specimens should be determined using a validated test method (see section 4.4)." (PMID 34790681, 2021). "In GBM, altered expression of EGFR membrane trafficking regulators, resulting in aberrant EGFR localisation, has been associated with tumour progression and therapy resistance to EGFR-targeted therapies." (PMID 34831480, 2021). "The frequency of smokers 0 pack-years (68.8%, 53/77) among patients with tumours having EGFR mutations was significantly higher than that among smokers 0–30 pack-years (50.0%) and smokers ≥30 pack-years (0.0%) (P<0.001)." (PMID 34804960, 2021). "Blockade of EGFR with specific tyrosine kinase inhibitors (TKIs) generates dramatic tumor responses and has shown significant efficacy in the treatment of patients carrying specific mutations in the EGFR TK domain in their tumor cells." (PMID 34459571, 2021). "A systemic review and meta-analysis of 32 studies with 4527 advanced NSCLC patients reported a pooled sensitivity and specificity of 0.70 and 0.98 respectively for ctDNA EGFR mutation status in plasma samples compared to tumor tissues." (PMID 34074295, 2021). "In the present study, we have identified loss of the PHLPP tumor suppressors as mechanisms of resistance to EGFR-TKI in NSCLC." (PMID 34168988, 2021). "Though T790M mutation causes resistance to early‐generation EGFR TKIs, it is associated with slower tumor growth and better prognosis." (PMID 34977873, 2021). "LRIG1 encodes a protein that negatively regulates epidermal growth factor receptor signaling, and its tumor-suppressive effects in cancer have been demonstrated." (PMID 34172056, 2021). "Quercetin inhibited the tumor growth of xenografted NSCLC cells harboring the EGFR C797S mutation and appeared to act synergistically with brigatinib to inhibit of tumor growth in vivo." (PMID 34572484, 2021). "Other studies used tumor-associated antigens such as EGFR and EpCAM that are present on vital healthy tissues, leading to toxicities if targeted systemically." (PMID 33863363, 2021). "The identification of mutations within the EGFR gene in tumor tissues is acknowledged to be the most effective method of estimating the efficiency of treating NSCLC with EGFR-TKIs." (PMID 33855679, 2021). "PDX1, harboring the Del19 EGFR mutation, was treated with afatinib (Afa), resulting in an increased tumor growth inhibition (TGI) up to 131.52% in 3 weeks." (PMID 33972544, 2021). "Tumours with uncommon EGFR mutations showed a significantly higher TMB than those with common EGFR mutations (11.2 vs. 3.1 muts/Mb, p < 0.01)." (PMID 33889543, 2021). "These tumors also harboured distinct EGFR 19Del versus BRAF V601E driver mutations plus multiple unique non-synonymous mutations in each tumor, resulting in a high-probability classification of MPLC with coincidental TERT Amplification." (PMID 34109114, 2021).
tumor (continued). "An inferior survival after relapse for the panitumumab treated patients was observed, especially for the population with a mutation (either KRAS, BRAF, NRAS or PIK3CA), possibly due to accelerated tumour growth caused by the anti-EGFR therapy." (PMID 34253874, 2021). "The tumour-intrinsic factors inversely associated with the reported score such as EGFR, PRKAR1A and MAP3K1 are frequently associated with immune-suppressive phenotypes." (PMID 33139798, 2021). "Due to its high level expression on the surface of various cancers, EGFR has been established as a docking protein for enhanced delivery of therapeutic and diagnostic agents to the tumor stroma with EGFR-overexpressing cancers." (PMID 34207383, 2021). "Because EGFR inhibition by cetuximab can inhibit intracellular-signaling pathways linked to dysregulated cell growth, the anti-tumor effects of cetuximab are expected to involve cell cycle arrest." (PMID 33664437, 2021). "Both EGFRvIII and EGFR vIVa mutations lead to constitutive EGFR signaling, tumor growth and progression pathways." (PMID 34285259, 2021). "Conversely, in those patients with an EGFR mutation detected via tumor biopsy, this result was confirmed in around 50% of cases." (PMID 34680416, 2021). "During this period, NGS testing revealed that the tumor was an EGFR exon 21 L858R point mutation, with an abundance of 8.68%." (PMID 34397683, 2021). "Analysis of The Cancer Genome Atlas (TCGA) and the Guangdong Lung Cancer Institute (GCLI) cohort have also confirmed an inverse correlation between EGFR mutation and PD-L1 expression in tumor tissues." (PMID 34113560, 2021). "The expression of HE4 is associated with cancer cell adhesion, migration and tumour growth, which can be related to its effects on the EGFR-MAPK signalling pathway." (PMID 33800113, 2021). "EGFR inhibitor treatment history and tumor mutation load are risk factors for the overall survival of patients with stage III/IV NSCLC who have undergone only hospice care." (PMID 33787673, 2021). "Uncontrolled EGFR activity (by overexpression or structural abnormalities in the receptor or its ligands) has been implicated in many aspects of tumour growth, including the promotion of cell proliferation, angiogenesis, invasion, metastasis and survival." (PMID 33889209, 2021). "The mutation status of Epidermal Growth Factor Receptor (EGFR) was suggested to be associated with the local tumor control of BM after GKRS." (PMID 34439186, 2021). "Many tyrosine kinase inhibitors (TKIs) have been developed to suppress the tumor‐promoting properties caused by EGFR mutations in non‐small‐cell lung cancer (NSCLC) patients." (PMID 33188726, 2021). "For this reason, third-generation TKIs were designed with the superiority of binding to EGFR-sensitive mutations and T790M mutation sites, subsequently inhibiting the tumor resistance caused by the T790M mutation." (PMID 34575576, 2021). "In this study, the prediction of EGFR mutation status was mainly based on the tumor area, similar to the result of previous studies." (PMID 34367993, 2021). "The broad specificity of 806 CAR T cells to EGFR alterations gives us the potential to target multiple clones within a tumor and reduce opportunities for tumor escape via antigen loss." (PMID 34568006, 2021). "A minimum of 200 tumor cells or 10% tumor content defined an adequate sample for EGFR mutation analysis." (PMID 33425564, 2021). "EGFR activation has also been associated with the induction of an immunosuppressive environment by the tumor cells, via up-regulation of pro-inflammatory cytokine secretion." (PMID 34211836, 2021). "Given that mutation of oncogene or tumor suppressor is a key driver in cancer cell-autonomous metabolic reprogramming, we therefore sought to determine the effect of EGFR mutation on the metabolomics profile of IAC patients." (PMID 34759281, 2021).
tumor (continued). "In this cohort, tumor mutation loads were more strongly affected by T790M mutation than by previous EGFR-TKI treatment response." (PMID 34373555, 2021). "Profiles describing the immune landscape of patients with EGFR mutations were characterized by differences in tumor mutation burden (TMB), ESTIMATE, CIBERSORT, and microenvironment cell populations-counter (MCP-counter)." (PMID 34136375, 2021). "The Spearman correlation coefficient between sensitizing EGFR mutation copy number and baseline tumor volume was ρ = 0.45 with p = 0.024." (PMID 34283064, 2021). "The clinical experience gained in the field of EGFR mutant NSCLC have shown that the EGFR gatekeeper mutation T790M can be present at low abundance in tumours prior to treatment and be difficult to detect." (PMID 34068816, 2021). "The association of both anti-VEGF and anti-EGFR monoclonal antibodies to chemotherapy increased the pathological tumor response rate." (PMID 33530435, 2021). "The results of mutation profiling using NGS showed that the S8 tumour had EGFR deletion 19, whereas the S9 and S10 tumours had EGFR L858R." (PMID 33707471, 2021). "First, we found that overexpressions of c-MET/EGFR were associated with the infiltration of tumor immune cells and cancer-associated fibroblasts, and were of prognostic relevance in CRC cohorts." (PMID 34512327, 2021). "At baseline, patients included in the FLAURA study were required to have tumor tissue EGFR mutated advanced NSCLC, and to have blood samples for retrospective central Cobas plasma cfDNA analysis of the EGFR status." (PMID 34638411, 2021). "The identification of novel biomarkers that are predictive of tumour relapse or TKI resistance is key to improving the health outcomes for NSCLC patients with tumours harbouring EGFR activating mutations." (PMID 34572879, 2021). "In the present study, afatinib showed favorable ORR and PFS regardless of the tumor EGFRm status results, similar to the findings of previous trials assessing afatinib as first‐line treatment of EGFR‐mutated NSCLC based on tumor genotyping." (PMID 33270375, 2021). "In contrast, tumours harbouring an exon 19 mutated EGFR exhibited lower levels of VEGFR1 (vascular endothelial growth factor receptor 1)." (PMID 34298636, 2021). "The only exception concerns EGFR T790M mutation detection in tumor or cfDNA at progression after treatment with an EGFR TKI of the first–second generation." (PMID 34638411, 2021). "At present, the mechanisms underlying the heterogeneity of anti-EGFR therapy-induced tumor responses observed in HNSCC patients remain ill-defined." (PMID 33485341, 2021). "Several reports have shown that overexpression of the epidermal growth factor receptor (EGFR) is strongly associated with tumour progression, migration, and invasion." (PMID 33551680, 2021). "EGFR mutations were more frequent in tumours with CTR ranging from 0.25 to 0.5 (85.7%, 12/14) and from 0.5 to 1 (66.7%, 20/30) than in those with CTR ranging from 0 to 0.25 (51.0%, 25/49) (P=0.048)." (PMID 34804960, 2021). "Activating EGFR mutations are found in up to 50% of NSCLC tumours from Asian populations, including in 30–40% of Japanese patients." (PMID 33648453, 2021). "The present study illuminates our understanding of how mutated EGFR correlate with modulated tumour immune responses." (PMID 35052732, 2021). "The occurrence of concomitant EGFR mutations in multiple tumours within the same individuals was significantly more frequent than expected by chance (P = 0.0023)." (PMID 33707471, 2021). "Based on these findings, the patient was treated with erlotinib, a tyrosine kinase inhibitor targeting the EGFR L858R mutation, and the tumor decreased considerably." (PMID 36939746, 2021). "After meeting the minimum requirements for detection, the EGFR mutation rate is affected by the proportion of tumor cells in the sample." (PMID 34034456, 2021).